RN7SKP22 (RN7SK pseudogene 22)
Gene: Miscellaneous RNA gene on chromosome 19 (32,862,800 to 32,863,092, reverse strand). Ensembl gene ENSG00000201967.
Homologues: Orthologues: chimpanzee 7SK (95% identical), mouse Gm56101 (70% identical). Paralogues in human: RN7SKP224 (80% identical), RN7SKP255 (78% identical), RN7SKP71 (78% identical), RN7SKP79 (78% identical), 7SK (78% identical), RN7SKP208 (77% identical), RN7SKP203 (76% identical), RN7SKP226 (76% identical), RN7SKP137 (76% identical), RN7SKP180 (76% identical), RN7SKP69 (76% identical), RN7SKP124 (76% identical), and 284 more.